CHD1L (chromodomain helicase DNA binding protein 1 like)
Diseases named in the same sentence as CHD1L in open-access papers (continued):
Sharing a sentence is not in itself a finding about the gene and the disease.
cancer (continued). "CHD1L is also an oncoprotein since its overexpression leads to dysregulation of related downstream targets in various cancers." (PMID 33663617, 2021). "The overexpression of CHD1L is also related to the clinical characteristics and prognosis of patients, so the expression level of CHD1L can be considered as a potential prognostic factor for cancer." (PMID 33663617, 2021). "Chromodomain-helicase-DNA-binding-protein 1-like gene (CHD1L) was identified to be frequently amplified at chromosome 1q21 in many cancers and characterized as a critical oncogenic driver in our previous studies." (PMID 34654797, 2021). "CHD1L overexpression in cancer cells is considered as a biomarker of short tumor-free survival time and poor prognosis." (PMID 33663617, 2021). "Here based on our previous study and the present study, we show that high expression of CHD1L plays a potential role in the inducement of EOC cancer cell invasion and/or metastasis via the regulation of METAP2 expression." (PMID 32922205, 2020). "Several genetic variants had high mutation rates across the entire study group in comparison with normal ovarian controls, e.g. recurrent deleterious variants in the CHD1L, GFM1, MEIS1 and NFX1 genes, suggesting specificity to cancer." (PMID 30416686, 2018). "By our analysis, we have identified novel regions of allelic imbalance that contain several cancer related genes such as CHD1L and S100A9 at locus 1q21.1; and CENPF and ESRRG at locus 1q32-q42." (PMID 26314549, 2015). "CHD1L-mediated transcriptional activation of target genes seems to play crucial roles during cancer development." (PMID 24359616, 2013). "All of this evidence strongly suggests that CHD1L functions as a driver gene during cancer development." (PMID 24359616, 2013). "Better understanding of CHD1L genomic functions will likely pave the way for novel therapeutic strategies (siRNA, small molecules) to modulate critical signaling pathways in cancer." (PMID 24359616, 2013). "In cancer cells, however, too much CHD1L can overly relax the chromatin, making the DNA vulnerable to mistake and thus raising the risk of cancer." (PMID 23020525, 2012). "CHD1L transgenic mouse model established in this study provides a very useful tool for investigating CHD1L function and role in cancer development." (PMID 19701453, 2009). "Furthermore, these findings align with those of other groups, in which CHD1L overexpression promotes G1-to-S phase transition and cancer cell survival." (PMID 40072047, 2025). "However, in highly proliferating cells such as cancer, CHD1L is activated through poly-ADP-ribose (PAR) binding to CHD1L’s macro domain." (PMID 40072047, 2025). "Importantly, its low expression in most normal tissues and cancer-specific upregulation position CHD1L as an attractive target for cancer drug development." (PMID 40442742, 2025). "This review covers CHD1L’s structure, oncogenic functions, and developmental origins, and highlights emerging therapeutic strategies that target CHD1L as a druggable vulnerability in cancer." (PMID 40442742, 2025). "Since its discovery, CHD1L has been further identified as a key biomarker and oncogenic protein in many cancers, including colorectal, breast, bladder, lung, and kidney cancers, indicating its crucial role in cancer progression." (PMID 40442742, 2025). "In conclusion, these findings suggested that VRK1/CHD1L/SNAI1 axis acts as a cancer-driving pathway to promote the proliferation and EMT of HCC, indicating that targeting VRK1 may be an attractive therapeutic strategy of HCC." (PMID 40234378, 2025). "However, the use of CHD1L genetic silencing in future cancer treatment has been proposed as a potential therapeutic avenue." (PMID 40442742, 2025). "Continued exploration of CHD1L’s roles across both normal and disease states will not only advance the basic understanding of chromatin dynamics but also drive the next generation of targeted cancer therapies." (PMID 40442742, 2025).
cancer (continued). "Among its oncogenic roles, CHD1L drives tumor progression and enhances tumor cell survival by promoting cell proliferation through the G1/S phase of the cell cycle, an effect that has been observed in various cancers, including BC and CRC." (PMID 40072047, 2025). "CHD1L has emerged as a promising molecular target to address this therapeutic gap due to its widespread overexpression and oncogenic activity across multiple types of cancer." (PMID 40442742, 2025). "However, this review places a primary focus on CHD1L’s role in cancer, where its overexpression and biochemical activity drive tumor progression, metastatic potential, therapeutic resistance, and poor clinical outcomes." (PMID 40442742, 2025). "A recent pan-cancer analysis comparing CHD1L expression in normal and tumor tissues suggests its overexpression may approach 100% in several cancers, including thyroid, colorectal, stomach, head and neck, prostate, ovarian, and skin cancers." (PMID 40442742, 2025). "In conclusion, since its discovery, CHD1L has emerged as an oncogene in many types of cancer." (PMID 39201277, 2024). "Although it has been established that CHD1L plays an important role in the progression of different types of tumors, there is a lack of studies that analyze the collective action of CHD1L in a group of tumors, and for this purpose, we present here the first systematic pan-cancer analysis of CHD1L." (PMID 37033447, 2023). "This complex status of the tumor confirms the requirement of a deep approach that can correlate a targeted gene with tumor progression through different points of analysis and for this purpose the current study applied a pan-cancer analysis for the oncogenic behavior of CHD1L." (PMID 37033447, 2023). "Since CHD1L was discovered in 2008, it acts as an oncogene in a variety of tumors, but relatively few reported CHD1L as a druggable target and establishes a novel therapeutic strategy for the treatment of cancers." (PMID 33663617, 2021). "ALC1 (amplified in liver cancer 1), also known as CHD1L (chromodomain-helicase-DNA-binding protein 1-like), is an ISWI-related chromatin remodeler encoded by a gene on chromosome 1q21, a region commonly amplified in many cancers." (PMID 33333017, 2021). "Further inhibition of CHD1L and its downstream autophagy signaling might shed new light on cancer therapeutics." (PMID 34654797, 2021). "Finally, we will conclude that CHD1L is an attractively clinical target in the future molecular therapy of cancer." (PMID 33663617, 2021). "All these findings proposed CHD1L as a very promising drug target for cancer treatment." (PMID 34654797, 2021). "Further inhibition of CHD1L and its downstream autophagy signaling might provide novel therapeutic strategy in cancer treatment." (PMID 34654797, 2021). "However, despite there being a clear connection between CHD1L and cell invasion/metastasis, the precise molecular mechanisms by which CHD1L promotes cancer cell invasion/metastasis are still unclear." (PMID 32922205, 2020). "Decreased apoptosis is another major mechanism of oncogenes involved in cancer development; we hypothesized that CHD1L might be involved in apoptosis in EC, and we assessed the effect of CHD1L on survival of EC cells by flow cytometry." (PMID 29088777, 2017). "The known functions of CHD1L in the literature are primarily related to cancers." (PMID 24885232, 2014). "Although CHD1L is implicated in the pathogenesis of several types of cancer, the expression of CHD1L and its significance in NPC have not been well documented." (PMID 25371726, 2014). "The transcriptional regulation of these genes by CHD1L could partially explain the mechanisms of CHD1L oncogenic role in cancer development which will be discussed in detail later." (PMID 24359616, 2013).
cancer (continued). "Therefore, small molecule inhibitors of CHD1L (CHD1Li) may be an effective strategy to treat cancer, particularly when used as a combination therapy with SOC chemotherapy and other targeted drug therapies." (PMID 39684869, 2024). "However, CHD1L is an oncoprotein, which is overexpression in various cancers." (PMID 33663617, 2021). "Therefore, this review suggests that CHD1L may be a novel biomarker for cancers and represents a fascinating target for molecular cancer therapy in the future." (PMID 33663617, 2021). "Our findings indicate that CHD1L plays a potential role in the inducement of EOC cancer cell invasion and/or metastasis via the regulation of METAP2 expression and suggests that CHD1L inhibition may provide a potential target for therapeutic intervention in human EOC." (PMID 32922205, 2020). "The molecular mechanism by which CHD1L regulates cancer cell cisplatin resistance remains unclear." (PMID 30718500, 2019). "Targeting Chromodomain Helicase DNA-Binding-Protein 1-Like (CHD1L), also known as Amplified in Liver Cancer-1 (ALC1), offers a promising strategy to combat these challenges and improve survival outcomes for cancer patients." (PMID 40072047, 2025). "Once activated, CHD1L regulates numerous oncogenic functions, including malignant gene expression, tumor cell plasticity via epithelial–mesenchymal transition (EMT), and cancer stem-cell stemness." (PMID 40072047, 2025). "The role of CHD1L in tumor progression, cell survival, metastasis, and MDR makes it an attractive molecular target for the next generation of cancer treatments." (PMID 40442742, 2025). "Our findings align with the existing literature, demonstrating that the pharmacological inhibition of CHD1L by OTI-611, either alone or in combination with standard therapies, presents a promising and effective approach for cancer treatment and overcoming MDR." (PMID 39201277, 2024). "Collectively, CHD1L’s oncogenic functions pose a formidable challenge to SOC chemotherapy and targeted drug therapies for the treatment of CRC and other cancers." (PMID 39684869, 2024). "Also, TMB and MSI were found to be correlated with CHD1L expression in some human cancers therefore these findings could nominate CHD1L as a prognostic biomarker, a marker for patients’ response to immunotherapy, and a potential target for cancer treatment." (PMID 37033447, 2023). "Following that, our study tried to reveal if there is a relation between CHD1L expression and the cancer stage where we found that LUAD, THCA, KIRP, and KIRC experienced a progression in the tumor stage with CHD1L expression." (PMID 37033447, 2023). "CHD1L (chromodomain helicase DNA binding protein 1-like), also called ALC1 (amplified in liver cancer 1), is a putative oncogene possibly involved in EOC located at chromosome 1q21." (PMID 32922205, 2020). "As a decreased binding peak of BTF3 was located in the promoter region of CHD1L and CHD1L has been reported as an oncogene in CRC and other cancer types, we chose CHD1L as a target candidate." (PMID 33644029, 2020). "CHD1L-induced SPOCK1 expression also contributes to tumor progression, with elevated SPOCK1 levels correlating with increased metastasis, advanced tumor stage, and poor clinical outcomes for cancer patients." (PMID 40442742, 2025). "Although several studies tried to analyze the oncogenic of CHD1L in several human cancers, there is a lack of a comprehensive study that can deal with the effect of CHD1L from many perspectives in a list of several human tumors." (PMID 37033447, 2023).
cancer (continued). "In this study, the results from in vitro and in vivo validation proved that nmMYLK, not smMYLK, is essential in CHD1L driven HCC cancer malignant phenotype, noticeable, all of these effects partially depended on LPS mimicked dysbacteriosis situation." (PMID 34588420, 2021). "Expression quantitative trait loci analysis revealed that rs9309336 and rs17160062 could regulate the expressions of cancer-related genes (PUS10 and CHD1L)." (PMID 31956354, 2020). "In order to determine any possible downstream targets of CHD1L in NSCLC cell cisplatin resistance, we analyzed mRNA expression of A549-CHD1L cells and its vector control, using Cancer Drug Resistance Real-time PCR Array containing 84 cell drug resistance-related genes." (PMID 30718500, 2019). "When come to the gene function of CHD1L, it has not been well clarified in human cancers except for HCC." (PMID 26360781, 2015). "In addition, CHD1L activity can be blocked by PARP-1 inhibitors, which have already been explored for use in cancer treatment." (PMID 25153161, 2014). "Notably, knockdown or inhibition of CHD1L consistently sensitizes tumor cells to chemotherapy and other targeted therapies, even in previously resistant models, positioning CHD1L as a compelling target to overcome MDR in a multitude of cancers." (PMID 40442742, 2025). "Taken in the context of our results here on the function of CHD1L in EOC cells, these observations indicate that METAP2 might be a potential downstream target in the aggressive behavior of CHD1L-mediated EOC, and as a result promotes cancer cell invasion and metastasis." (PMID 32922205, 2020). "For the cancer phenotypes, the reverse genetics models were enriched in DNA repair functions (p = 2×10−5, FDR p = 0.03) (POLG/FANCI, SLX4/FANCP, XRCC1, BRCA1, FANCA, CHD1L) while the additive model showed enrichment related to chromatid segregation (p = 4×10−6, FDR p = 0.005) (KIF25, PINX1)." (PMID 24349080, 2013). "However, CHD1L’s oncogenic role is not solely driven by its expression level; many cancers, regardless of CHD1L expression level, appear to rely on its biochemical activity to sustain cancer cell survival and progression." (PMID 40442742, 2025). "Although there are no FDA approved CHD1L-related treatments on the market to date, there are several that have been proposed or are currently in development that may well drive forward the field of targeted cancer therapy." (PMID 40442742, 2025). "In a study reporting germline PVs, among 1120 pediatric cancer patients neither MYO3A, MYO3B, or CHD1L were covered." (PMID 39037077, 2024). "Further, we found six genes—FOXL2, TNFAIP3, CHD1L, HRAS, KIT, CTCF—that occurred in 12 cases that are not on the top 20 list of any of the four common cancers used for comparison." (PMID 32570879, 2020).
tumor (39 papers, 2009 to 2025). "Overexpression of CHD1L is common across a wide range of solid tumors and is strongly associated with tumor progression, metastatic potential, and poor prognosis." (PMID 40442742, 2025). "Higher levels of CHD1L are associated with increased tumor volume and grade, as well as lower overall median survival time." (PMID 40442742, 2025). "We also found that CHD1L expression is positively associated with tumor progression in HCC patients." (PMID 30718500, 2019). "Our data suggest that CHD1L overexpression is likely associated with aggressive tumor biology in EC." (PMID 29088777, 2017). "The Cdc42-specific GEF ARHGEF9 is up-regulated by the oncogene transcription factor CHD1L and has been previously implicated in tumor cell migration, invasion and metastasis by increasing cell motility and inducing filopodia formation." (PMID 26633832, 2015). "Amplification of CHD1L gene was significantly associated with CHD1L protein overexpression (P < 0.001) and tumor histology (P = 0.020)." (PMID 26360781, 2015). "Taken together, these observations suggest that overexpression of CHD1L in hepatocytes promotes the susceptibility of tumor formation in mouse." (PMID 19701453, 2009). "Finally, we applied the “compare tumor, normal, and metastasis” module of the TNMplot web server to associate the CHD1L mRNA expression level with the metastasis." (PMID 37033447, 2023). "In mESCs, overexpression of CHD1L increases tumor susceptibility." (PMID 33663617, 2021). "Our recent evidences from chromatin Immunoprecipitation (ChIP) of CHD1L followed by high-throughput sequencing indicated that CHD1L might also be closely associated with tumor cell autophagy." (PMID 34654797, 2021). "Functional annotation suggested the potential regulatory role of rs17160062 and C allele of rs17160062 was associated with an increased expression of CHD1L, the expression of which was significantly higher in tumor samples compared with that in the adjacent tissues." (PMID 31956354, 2020). "Furthermore, studies have shown that CHD1L expression was significantly associated with venous infiltration, microsatellite tumor nodule formation, an advanced tumor stage and poor survival in HCC." (PMID 25371726, 2014). "Association of patient and tumor characteristics with CHD1L expression." (PMID 25153161, 2014). "Furthermore, overexpression of CHD1L in hepatocytes could promote tumor susceptibility in CHD1L-transgenic mice." (PMID 24359616, 2013). "In addition, alcohol intoxication was used to induce hepatocyte pathological lesions and results found that overexpression of CHD1L in hepatocytes could promote tumor susceptibility in CHD1L-transgenic mice." (PMID 19701453, 2009). "CHD1L promotes tumor cell survival by upregulating SPOCK1 (see Control of Gene Expression and Signaling above), a matricellular glycoprotein that blocks apoptosis through activation of the PI3K/Akt signaling pathway." (PMID 40442742, 2025). "While multiple CHD1Li have demonstrated promising preclinical activity, mechanistic studies of OTI-611 have provided the most detailed evidence to date of CHD1L-dependent reprogramming of tumor cell death." (PMID 40442742, 2025). "In parallel, CHD1L has emerged as a master regulator of tumor cell survival by regulating DNA damage response and repair and enforcing G1 cell cycle progression." (PMID 40442742, 2025). "Mechanistically, CHD1L promotes tumor growth through modulation of DNA damage repair, activation of survival and cell cycle pathways, regulation of EMT, and suppression of both apoptotic and non-apoptotic forms of cell death." (PMID 40442742, 2025). "CHD1L has recently been characterized as a driver gene, and hence plays vital roles in tumor progression and sorafenib resistance of HCC." (PMID 40234378, 2025).